Y_RNA (Y RNA )
Gene: Miscellaneous RNA gene on chromosome 4 (87,743,952 to 87,744,053, reverse strand). Ensembl gene ENSG00000200024.
Homologues: Orthologues: chimpanzee Y_RNA (100% identical), macaque Y_RNA (91% identical), guinea pig Y_RNA (88% identical). Paralogues in human: RNY3P1 (90% identical), Y_RNA (90% identical), RNY3 (89% identical), Y_RNA (89% identical), Y_RNA (88% identical), Y_RNA (87% identical), Y_RNA (86% identical), RNY3P11 (85% identical), RNY3P9 (85% identical), Y_RNA (85% identical), RNY3P10 (84% identical), RNY3P14 (84% identical), and 95 more.